MIR1228 (microRNA 1228)
Synonyms: hsa-mir-1228; MIRN1228; mir-1228
Gene: MicroRNA gene on chromosome 12 (57,194,504 to 57,194,576, forward strand). Ensembl gene ENSG00000221365.
Homologues: Orthologues: chimpanzee MIR1228 (100% identical).
Diseases named in the same sentence as MIR1228 in open-access papers:
MIR1228 is named in the same sentence as 1 disease in open-access papers, as found by Europe PMC text mining. Sharing a sentence is not in itself a finding about the gene and the disease. The quoted sentences say what the papers report.
tumor (1 paper, 2020). "MIR133b, MIR1247, and MIR1228 expression was not increased in the tumor tissue in comparison to matched adjacent nontumor tissue (cohort 1, n = 29)." (PMID 31879968, 2020).